CALR (calreticulin)
Diseases named in the same sentence as CALR in open-access papers (continued):
Sharing a sentence is not in itself a finding about the gene and the disease.
dilated cardiomyopathy (6 papers, 2006 to 2025). Cardiomyopathy which is characterized by dilation and contractile dysfunction of the left and right ventricles. "We showed here that calreticulin, an ER associated Ca2+ buffering chaperone, is capable of inducing dilated cardiomyopathy in vivo." (PMID 23437120, 2013). "Although the overexpression of calreticulin in cardiomyocytes induces dilated cardiomyopathy (DCM) in animals, elevated levels of anti-calreticulin antibodies were noted in the sera of patients with both DCM and HCM." (PMID 40564271, 2025). "There is a strong correlation between calreticulin overexpression and high prevalence of atrial fibrosis in patients with dilated cardiomyopathy." (PMID 27441395, 2016). "In a recent work, the product of the CALR gene, calreticulin, has been shown to localize in cardiomyocyte mitochondria, and its content increases in mouse models with dilated cardiomyopathy." (PMID 25353622, 2014). "Taken together, the ECG analysis further supported our conclusion that up-regulation of calreticulin in adult heart leads to dilated cardiomyopathy and a significant impairment of systolic and diastolic function." (PMID 23437120, 2013). "Calreticulin induced dilated cardiomyopathy in adult hearts is likely due to an alterations in the expression of a subset of Ca2+ handling genes, as well as changes in gap junction components and left ventricle remodeling." (PMID 23437120, 2013). "In summary, we show that calreticulin induces dilated cardiomyopathy in the adult heart in transgenic mice, and induces “remodeling” of the SR Ca2+-cycling proteins and gap junctions." (PMID 23437120, 2013). "ER membrane components, including calreticulin, may represent novel targets for development of pharmacological compounds to intervene with induction of dilated cardiomyopathy and remodeling of Ca2+-handling mechanisms in the heart." (PMID 23437120, 2013). "In addition, the drug promotes increased expression of calreticulin and calsequestrin, which are involved in the sarcoplasmatic reticulum calcium pump and decrease cell contractility, which in vivo may lead to dilated cardiomyopathy in mice and humans." (PMID 16839426, 2006). "In contrast, an increase in calsequestrin expression does not induce dilated cardiomyopathy and does not impact on expression of calreticulin." (PMID 23437120, 2013).
erythrocytosis (6 papers, 2020 to 2025). "Despite the role of STAT5 in JAK2-driven MPN promoting a PV phenotype, CALR mutation is unable to induce polycythemia or ligand independence when co-expressed with the EPO receptor." (PMID 32823933, 2020). "It revealed a frequent association between the JAK2 GGCC haplotype, a germline combination of single nucleotide polymorphisms (SNPs) and a CALR SNP (rs1049481, G > T) with an unknown biological significance in cases of erythrocytosis." (PMID 37239426, 2023). "Through association analysis, we show that male patients presenting with idiopathic erythrocytosis, and normal EPO levels could be the best candidates for the search for the JAK2 GGCC_46/1 haplotype and CALR rs1049481_G allele." (PMID 36031623, 2022).
nasopharyngeal carcinoma (6 papers, 2017 to 2022). A carcinoma arising from the nasopharyngeal epithelium. "We investigated the expression and clinical significance of CALR in nasopharyngeal carcinoma (NPC)." (PMID 31632490, 2019). "In our previous study, five different secretory proteins, including GSN, ADAMTSL4, CALR, PPIA and TXN, have been identified to be associated with the nasopharyngeal carcinoma (NPC) metastasis." (PMID 28107202, 2017). "EBV drives NPC metastasis through EBV-encoded LMP1-mediated metabolic reprogramming via activation of IGF1-mTORC2 signaling and nuclear acetylation of the Snail promoter by PDHE1α, LMP1 upregulates calreticulin to induce EMT via the TGF-β/Smad3/NRP1 pathway in nasopharyngeal carcinoma cells." (PMID 35388172, 2022).
sarcoma (6 papers, 2015 to 2025). A usually aggressive malignant neoplasm of the soft tissue or bone. "Last, our experimental results proved that CALR was up-regulated in sarcoma cells compared to in normal cell." (PMID 40978026, 2025). "While endogenous CALR protein (~55 kDa) was detectable at low levels in all untreated sarcoma cell lines, its expression was markedly increased in the OE-CALR group." (PMID 40978026, 2025). "CALR mRNA levels were significantly elevated in all sarcoma cells compared to hFOB1.19 (p < 0.05 for MG-63, p < 0.01 for 143B and HOS; one-way ANOVA), indicating a consistent upregulation of CALR in malignant cells." (PMID 40978026, 2025). "To determine the differential expression of CALR between sarcoma and normal cells, we performed qRT-PCR analysis on three sarcoma cell lines (MG-63, 143B, HOS) and the human normal osteoblast cell line hFOB1.19." (PMID 40978026, 2025). "Western blot analysis of untreated sarcoma cells (Saos-2, MG-63, 143B, U2OS) and CALR-overexpressing 143B cells (OE-CALR) revealed distinct expression profiles." (PMID 40978026, 2025). "In cellular experiments, we observed significantly upregulated mRNA expression of CALR, CASP3, BCL10, PSMD7, and PSMD10 in sarcoma cell lines compared to their corresponding normal cell lines." (PMID 39469643, 2024). "According to the results of Kaplan-Meier analysis, higher CALR expression correlated with worse RFS in KIRC, liver hepatocellular carcinoma (LIHC), lung squamous cell carcinoma (LUSC), kidney renal papillary cell carcinoma (KIRP) and sarcoma (SARC)." (PMID 34910788, 2021).
Sepsis (6 papers, 2019 to 2025). Sepsis is defined as life-threatening organ dysfunction caused by a dysregulated host response to infection. "This study was aimed at investigating whether plasma calreticulin level increases in sepsis and its association with sepsis severity." (PMID 31612071, 2019). "Notably, the Kaplan–Meier survival curves demonstrated that sepsis patients with calreticulin levels above 343.5 pg/ml were at a greater risk of death than others." (PMID 31612071, 2019). "Moreover, we identified that increasing calreticulin levels was associated with higher mortality in sepsis patients." (PMID 31612071, 2019). "Moreover, plasma calreticulin levels were associated with increased risk of mortality in sepsis." (PMID 31612071, 2019). "Among other significant methylated genes of interest in the context of neonatal sepsis, we also found CALR, which codes for calreticulin, an endoplasmic reticulum resident protein, with functions in leukocyte migration and related with the severity of sepsis." (PMID 33659006, 2021). "Continuous monitoring of plasma calreticulin levels would more precisely and thoroughly show a correlation between calreticulin and sepsis severity." (PMID 31612071, 2019). "Our study examined the correlation between baseline plasma calreticulin levels and the severity of sepsis." (PMID 31612071, 2019). "Plasma calreticulin level was correlated with sepsis mortality in the univariate Cox regression model." (PMID 31612071, 2019). "Because of the correlation observed between calreticulin levels and sepsis severity, ROC curves and survival analysis were performed to investigate the predictive value of calreticulin for sepsis mortality." (PMID 31612071, 2019). "Second, calreticulin levels of sepsis patients were measured only in the first 48 hours after admission." (PMID 31612071, 2019). "Calreticulin level was positively correlated with the severity of sepsis, and increased calreticulin level indicated poor prognosis of patients with sepsis." (PMID 31612071, 2019). "Considering this factor, prospective and multicenter observational studies will be needed to understand the exact value of calreticulin in predicting sepsis mortality." (PMID 31612071, 2019). "Animal models of sepsis are needed to further explore the mechanism by which calreticulin levels increase in sepsis." (PMID 31612071, 2019). "Further studies on the role of calreticulin in sepsis are required." (PMID 31612071, 2019). "High levels of calreticulin are correlated with the severity of sepsis as proven in our study, which may reflect the active role of calreticulin in apoptosis and immune dysfunction in sepsis." (PMID 31612071, 2019). "Thus, this study was aimed at investigating the plasma levels of calreticulin in sepsis patients and the potential correlations between plasma calreticulin levels and sepsis severity." (PMID 31612071, 2019). "Third, the pathophysiological role of calreticulin in sepsis remains to be completely understood." (PMID 31612071, 2019). "Second, calreticulin levels in sepsis could provide important clinical information including sepsis severity that can be beneficial for clinical decision-making." (PMID 31612071, 2019). "High calreticulin level indicated poor prognosis of sepsis patients." (PMID 31612071, 2019). "Calreticulin was significantly increased in sepsis patients than in healthy controls." (PMID 31612071, 2019). "Neutralizing high levels of calreticulin in sepsis may provide a targeted treatment modality in sepsis." (PMID 31612071, 2019). "However, little is known about the role of calreticulin in sepsis with a characteristic of immune disorder." (PMID 31612071, 2019). "We found that plasma calreticulin levels could predict 28-day sepsis mortality, with an area under the ROC curve (AUC) of 0.664 (p = 0.003)." (PMID 31612071, 2019). "Sepsis patients were stratified according to calreticulin levels above and below 343.5 pg/ml." (PMID 31612071, 2019).
Sepsis (continued). "Calreticulin level was positively correlated with the severity of sepsis." (PMID 31612071, 2019). "Calreticulin may be used as a predictor of sepsis mortality according to the following advantages." (PMID 31612071, 2019). "However, little is known about the role of calreticulin in sepsis in a clinical context." (PMID 31612071, 2019). "In addition, calreticulin was correlated with the severity of sepsis according to our results." (PMID 31612071, 2019). "Thus, calreticulin released into the extracellular space may play an important role in immunogenic cell death and inflammatory diseases, which are the key features of sepsis." (PMID 31612071, 2019). "In the acute hyperinflammatory phase, distinct subsets of monocyte-like cells (CD163+SLC39A8+CALR+ infMonos) and Tinf cells (MX1+IRF1+ISG15+) emerged, a phenomenon also observed in patients with sepsis and COVID-19." (PMID 40251340, 2025). "The cleaved soluble transcription factor p50 ATF6 was significantly increased in the sepsis group, then free to translocated to the nucleus where it subsequently activated ER stress responsive genes, such as GRP78, GRP94, calreticulin, and CHOP44." (PMID 36088483, 2022). "We found significantly higher plasma calreticulin levels in nonsurvivors than in both healthy persons and sepsis survivors." (PMID 31612071, 2019).
amyotrophic lateral sclerosis (5 papers, 2013 to 2023). Amyotrophic lateral sclerosis (ALS) is a neurodegenerative disease characterized by progressive muscular paralysis reflecting degeneration of motor neurons in the primary motor cortex, corticospinal tracts, brainstem and spinal cord. "Amyotrophic lateral sclerosis (ALS) linked mutant FUS induce ER stress, and overexpression of mutant FUS colocalized with calreticulin (as a marker of ER) in NSC-34 motor neuron cells." (PMID 36875699, 2023). "Previous studies performed in amyotrophic lateral sclerosis reported that calreticulin-overexpressing cells display an increased total amount of [Ca2+]ER, as well as elevated ER Ca2+-pumping activity." (PMID 35159043, 2022).
Chagas disease (5 papers, 2013 to 2017). A parasitic infection caused by Trypanosoma cruzi. "On the other hand, Trypanosoma cruzi (the agent of Chagas’ disease) calreticulin (TcCRT) displays remarkable anti-angiogenic properties." (PMID 24755644, 2014).
esophageal cancer (5 papers, 2017 to 2022). A primary or metastatic malignant neoplasm involving the esophagus. "CALR also upregulated neuropilin-1 expression via STAT5A in esophageal cancer cells." (PMID 35641480, 2022). "CALR promotes migration and invasion of esophageal cancer cells by up-regulating neuropilin-1 expression via STAT5A and neuropilin-1 is a critical downstream effector of CALR in promoting cell migration and invasion." (PMID 29228584, 2017).
lung adenocarcinoma (5 papers, 2017 to 2022). A carcinoma that arises from the lung and is characterized by the presence of malignant glandular epithelial cells. "The (Cancer Genome Atlas) databases were adopted to evaluate the expression status of CALR in pan-cancer, including Lung adenocarcinoma (LUAD) and Lung squamous cell carcinoma (LUSC) accompanied with Genotype-Tissue Expression project (GETx) database." (PMID 35264066, 2022). "GEPIA data showed that CALR was significantly upregulated in lung adenocarcinoma (LUAD) and lung squamous cell carcinoma (LUSC) tissues compared to normal lung tissues." (PMID 34660305, 2021). "Of note, (R)-crizotinib was more efficient than its enantiomer (S)-crizotinib in inducing CALR-RFP redistribution and pyknosis in U2OS cells, as well as in mouse fibrosarcoma MCA205 and lung adenocarcinoma TC1 cells." (PMID 30940805, 2019).
parasite infection (5 papers, 2013 to 2024). "CALR contributes to parasite infection by interfering with the initial phase of host complement activation." (PMID 39770348, 2024). "Several protozoa and multicellular parasites have been found to express calreticulin on the body surface and even secrete calreticulin in vitro, which plays an important role in parasite–host interactions; in particular, it is closely related to parasite infection and host immune response." (PMID 38026665, 2023). "While some evidence supports the involvement of SR-AI and MARCO in parasite infection (Schistosoma japonicum and Leishmania major, respectively), the ability of SR-AI to directly recognize helminth components has only been shown for Heligmosomoides polygyrus calreticulin." (PMID 30500820, 2018).
acute lymphoblastic leukemia (4 papers, 2016 to 2024). Leukemia with an acute onset, characterized by the presence of lymphoblasts in the bone marrow and the peripheral blood. "After 70 months of follow-up, ALPK1, ACTN4, CALR, and ZNF695 were identified as potential prognostic risk factors for adult acute lymphocytic leukemia in the overall survival analysis." (PMID 36139553, 2022). "ALPK1, ACTN4, CALR, ZNF695, and FBXL5 were identified as novel prognostic genes in relapsed acute lymphoblastic leukemia." (PMID 36139553, 2022).
Alzheimer disease (4 papers, 2013 to 2023). A progressive, neurodegenerative disease characterized by loss of function and death of nerve cells in several areas of the brain leading to loss of cognitive function such as memory and language. "Ultimately, three proteins associated with Alzheimer’s disease were selected: 14-3-3 protein zeta/delta, low-density lipoprotein-receptor-related protein 1B (LRP1B), and calreticulin." (PMID 37630190, 2023). "Calreticulin is down-regulated in the cortical neurons of patients with Alzheimer’s disease (AD) and may be a potential biomarker for the diagnosis of AD." (PMID 25429433, 2014). "Moreover, recent research has suggested that calreticulin functions as a negative biomarker of Alzheimer’s disease, indicating its positive role in preventing the disease." (PMID 37630190, 2023). "Calreticulin is an intracellular chaperone, which can bind Aβ, but it is not known whether calreticulin can act as extracellular chaperone for Aβ, which would be particularly relevant for Alzheimer’s disease." (PMID 35514983, 2022).
Arterial thrombosis (4 papers, 2023 to 2026). The formation of a blood clot inside an artery. "While arterial thrombosis is a recognized complication of ET, CALR-mutated ET is typically associated with a lower thrombotic risk compared to JAK2-mutated disease." (PMID 40278216, 2025). "CALR-positive ET, as per the 2016 WHO classification, represents a distinct molecular subset of ET with a generally lower thrombotic risk profile, yet this case illustrates that such patients may still present with arterial thrombosis in atypical ways." (PMID 40278216, 2025).
asthma (4 papers, 2012 to 2024). "GANAB and CANX belong to endoplasmic reticulum protein chaperones, which cooperate with CALR to regulate endoplasmic reticulum stress in osteoarthritis and asthma, respectively." (PMID 34910788, 2021). "Therefore, the decrease of the C/EBPα protein level in BSM cells of asthma patients may only partially be related to increased calreticulin." (PMID 22500186, 2012).
Autoimmunity (4 papers, 2012 to 2023). The occurrence of an immune reaction against the organism's own cells or tissues. "MBL binds calreticulin which plays a role in antigen presentation and serves as a trigger for innate immune responses in autoimmunity, DC maturation, and T cell responses." (PMID 22762710, 2012). "However, recent reports of PNH arising in the setting of a CALR-mutated MPN,CML and a relapse of AML associated with TET2 and JAK2 mutations raise the question of whether autoimmunity is necessary in all cases." (PMID 31453016, 2019). "It has been reported that adenomyosis is associated with the presence of autoantibodies, in particular to phospholipids; however, it is not known whether it is associated with autoimmunity to calreticulin." (PMID 26425587, 2013).
B-cell lymphoma (4 papers, 2015 to 2025). "In this study, we screened a library of five pyrrole–imidazole polyamides coding for different DNA sequences in a model of B-cell lymphoma for the upregulation of surface calreticulin, a pro-phagocytosis signal implicated in immunogenic cell death." (PMID 26537405, 2015). "MPM-1 also induced release of the DAMPs adenosine triphosphate (ATP) and high mobility group box 1 (HMGB1) from Ramos (B-cell lymphoma) and HSC-3 cells, as well as cell surface expression of calreticulin in HSC-3 cells." (PMID 36114339, 2022).
cardiomyopathy (4 papers, 2013 to 2025). A disease of the heart muscle or myocardium proper. "Calreticulin increases cardiomyocyte endoplasmic reticulum/sarcoplasmic reticulum Ca2+ capacity and mechanical work potential, but at the same time may lead to cardiomyopathy, reduce cell–cell communication, and induce increased collagen deposition and cardiac fibrosis." (PMID 40564271, 2025).
eosinophilia (4 papers, 2020 to 2025). "Mice injected intraperitoneally with free calreticulin showed a 43–49% decrease in worm burdens in the lungs, with low serum IgE levels and intermediate levels of lung eosinophilia." (PMID 32171305, 2020). "Mice immunized with hookworm calreticulin intraperitoneally without adjuvant produced 43–49% fewer worms in their lungs following a hookworm larva challenge associated with low levels of serum IgE and moderate lung eosinophilia." (PMID 36288020, 2022). "However, calreticulin encapsulated in poly-lactide-coglycolide microparticles induced anti-calreticulin IgG1 and IgE levels and lung eosinophilia higher than that induced by free calreticulin but without protective immunity." (PMID 32171305, 2020).